CCL4 (C-C motif chemokine ligand 4)
Diseases named in the same sentence as CCL4 in open-access papers (continued):
Sharing a sentence is not in itself a finding about the gene and the disease.
autoimmune disease (6 papers, 2021 to 2025). A disorder resulting from loss of function or tissue destruction of an organ or multiple organs, arising from humoral or cellular immune responses of the individual to their own tissue constituents. "Wondering which hub gene is previously considered as the potential pathogenic manipulator for autoimmune disease in references, we retrieved PubMed and only to find CCL4, as a central hub gene, stands out in RA, MS and BD etiology." (PMID 34975900, 2021). "Elevated levels of CCL4 have been detected in patients with autoimmune diseases, suggesting its potential role in mediating immune responses linked to thrombocytopenia." (PMID 40261473, 2025). "As the similar pathogenesis existing among autoimmune diseases, we could deduce that the expression of CCL4 might be a circulating inflammatory chemokine which aggravates inflammation and disease progression via inducing immune cell infiltration and damaging surrounding tissue in BD patients." (PMID 34975900, 2021).
endothelial dysfunction (6 papers, 2015 to 2025). In vascular diseases, endothelial dysfunction is a systemic pathological state of the endothelium (the inner lining of blood vessels) and can be broadly defined as an imbalance between vasodilating and vasoconstricting substances produced by (or acting on) the endothelium. "As shown by a study from Mathieu Nacher, dendritic cells infected by DENV express CCL4, which is associated with vasodilation, endothelial dysfunction, and disease severity." (PMID 34394108, 2021). "CCL4 also could contribute to the age-related endothelial dysfunction provoked by oxidative stress and exhausted enzymatic systems of DNA repair, as well as endothelial inflammation." (PMID 40149697, 2025).
epilepsy (6 papers, 2013 to 2024). A brain disorder characterized by episodes of abnormally increased neuronal discharge resulting in transient episodes of sensory or motor neurological dysfunction, or psychic dysfunction. "Previous studies in rats have found that Ccl4 gene and protein expression are acutely increased in epilepsy, including in astrocytes." (PMID 38600221, 2024). "Although a relationship between CCL4 and epilepsy is unclear, a relationship between epilepsy and immune response has been suggested." (PMID 24282673, 2013). "The scRNA‐seq of non‐affected brain areas of patients with epilepsy revealed 10 distinct microglial clusters, with the genes CCL2, CCL4, and SPP1 being involved." (PMID 38572804, 2024). "We measured the serum interictal quantitative levels of chemokines (CCL2, CCL4, CCL11) and PGE2 in correlation with the seizure frequency and severity in controlled and intractable childhood epilepsies." (PMID 36291442, 2022). "Indeed, inflammatory mediators may be relevant for the pathogenesis of epilepsy in FCD, as confirmed by the reported up-regulation of inflammatory cytokines and their receptors and/or downstream effectors (such as IL-1β, IL-6, CCL3, CCL4, STAT3, C-JUN and CCR5) in this disease." (PMID 35741692, 2022).
heart failure (6 papers, 2022 to 2025). Inability of the heart to pump blood at an adequate rate to meet tissue metabolic requirements. "DNMT3A mutated monocytes from patients with heart failure have been shown to express higher mRNA levels of IL-1β, IL-6 and IL-8, macrophage inflammatory chemokines CCL3 and CCL4 and the inflammasome NLRP3." (PMID 36835370, 2023).
Hepatic steatosis (6 papers, 2017 to 2024). Steatosis is a term used to denote lipid accumulation within hepatocytes. "Diabetic KK-A, leptin-resistant (db/db) and leptin-deficient (ob/ob), high fat and high fructose diet-fed mice all of which exhibit hepatic steatosis, have all been reported to demonstrate impeded regeneration after hepatectomy or CCL4 administration." (PMID 28129776, 2017). "However, in the 15-week CCL4-exposed and 24-week HFFC diet-fed mice, Nrf2 induction with bardoxolone reduced liver steatosis, inflammation, fibrosis, and proliferation." (PMID 39125617, 2024). "The mice developed hepatic steatosis, severe hepatic inflammation, and fibrosis by BDL or CCL4." (PMID 29670908, 2018).
Hyperglycemia (6 papers, 2021 to 2025). An increased concentration of glucose in the blood. "Recently, CCL4 inhibition was shown to improve ischemia-induced neovasculogenesis in different types of diabetic mice, suggesting the general role of CCL4 in vasculopathy in the presence of hyperglycemia." (PMID 33968046, 2021). "The findings suggest the novel and common roles of CCL4-related inflammation in the progression of hyperglycemia in different experimental DM." (PMID 33968046, 2021). "Our findings not only elucidate the potential role of CCL4-related inflammation in the progression of hyperglycemia but also provide some novel mechanistic clues to the deterioration of blood sugar levels in the presence of DM." (PMID 33968046, 2021). "Indeed, CCL4 inhibition has demonstrated benefits in reducing hyperglycemia progression and improving insulin sensitivity." (PMID 41030257, 2025). "In support of these observations, another study which also utilised anti‐Ccl4 antibodies reported that Ccl4 inhibition improved insulin sensitivity and lipid profiles, delayed the progression of hyperglycaemia and reduced systemic inflammation in high‐fat diet‐fed mice." (PMID 36245259, 2022). "In this study, both in vivo and in vitro experiments were conducted to investigate whether directly inhibiting CCL4 could retard the progression of hyperglycemia in different animal models and directly protect pancreatic β-cells." (PMID 33968046, 2021). "Our findings may hopefully elucidate the particular role of CCL4-related inflammation in the progression of hyperglycemia and provide some novel rationale to the potential strategy targeting on CCL4 to improve blood sugar control in clinical DM." (PMID 33968046, 2021). "Hyperglycemia leads to an enhanced expression of chemokines in kidney tissue, such as CCL2, CCL3, CCL4, CCL5, and CXCL12, involving in immune cell recruitment and modulating the inflammation." (PMID 40046045, 2025). "While CCL4 may be related to systemic inflammation and vasculopathy individually in different types of DM, the potential role of CCL4 in hyperglycemia has not been clarified." (PMID 33968046, 2021).
leukemia (6 papers, 2015 to 2024). A malignant (clonal) hematologic disorder, involving hematopoietic stem cells and characterized by the presence of primitive or atypical myeloid or lymphoid cells in the bone marrow and the blood. "Both Ibrutinib and Acalabrutinib have been shown to decrease levels of CCL3 and CCL4, two critical chemokines inducing migration or homing of leukemia cells, in CLL-cell cultures and their separate clinical trials." (PMID 34174847, 2021). "This is the first report on the important role of ARC in the regulation of the CCR2/CCL2 and CCR5/CCL4 axes in leukemia and stromal cells." (PMID 26956049, 2016). "We identify that, in addition to the well-known CXCR4/CXCL12 axis, CCR2/CCL2 and CCR5/CCL4 also drive leukemia/stromal interactions." (PMID 26956049, 2016). "ARC upregulated IL1β in AML cells and increased the levels of CCL2, CCL4, and CXCL12 in MSCs by activating the NFκB pathway, thereby promoting the migration and adhesion of leukemia cells to MSCs." (PMID 39351758, 2024).
lupus (6 papers, 2020 to 2025). "Moreover, in Systemic Lupus Erythematosus (SLE) a pathogenic three-marker signature, including high levels of IL-1Ra and CCL4, was identified in monocytes." (PMID 32849645, 2020). "Previous studies have shown that Fli-1 is a positive regulator of CCL2, CCL3, CCL4, CCL5, CXCL9, and CXCL10 in the kidneys of Fli-1 heterozygote knockout mice with lupus and CXCL5 in dermal small vessels from Fli-1 knockout mice." (PMID 40305194, 2025). "We also found that expression of CCL2, CCL3, CCL4, CCL5, CCL8, CCL19, and CXCL10 increased 1.6–5.6-fold in the kidney of lupus-prone MRL.Faslpr mice with advancing age from 9 to 16 weeks." (PMID 37567910, 2023). "In lupus-prone NZB/W F1 mice, T cells and monocytes expressing CCR1 and CCR5 migrate to the kidney via sensing CCL3, CCL4, and CCL520." (PMID 37567910, 2023). "We found that expression of CCL2, CCL3, CCL4, CCL5, CCL8, CCL19, and CXCL10 increased 1.6–5.6-fold in the kidney of lupus-prone MRL.Faslpr mice with advancing age from 9 to 16 weeks." (PMID 37567910, 2023). "For example, secretion levels of CCL2, CCL3, CCL4, CCL5, CCL19, CXCL10, and CXCL12 are increased in the kidney of lupus-prone mice and SLE patients during the development of nephritis." (PMID 37567910, 2023).
type 2 diabetes (6 papers, 2016 to 2025). "Specifically, patients with type 2 diabetes showed a significant decrease in IL-9 (U = 389, P < 0.001) and CCL4 (U = 774.5, P < 0.001) concentrations compared to control participants." (PMID 41030257, 2025). "In both the type 2 diabetes and metabolic syndrome models, treatment with the CCL4 antibody increased pancreatic insulin expression, and reduced circulating insulin, TNF-α, and IL-6 levels." (PMID 33968046, 2021). "Reduced CCL4 concentrations may be observed in patients with type 1 and type 2 diabetes, the incidence of both being lower in Yakutia." (PMID 39769502, 2024). "Insulin infusion could suppress the CCL4 expression in mononuclear cells from patients with type 2 diabetes." (PMID 33968046, 2021). "Interestingly, in type 2 diabetic patients, insulin infusion could significantly suppress the expression of CCL4 in mononuclear cells." (PMID 27553774, 2016).
AIDS (5 papers, 2014 to 2021). A syndrome resulting from the acquired deficiency of cellular immunity caused by the human immunodeficiency virus (HIV). "Even though, clear mechanistic differences between CCL4 and CCL5 interaction with CCR5 are missing, even considering the knowledge gained on CCR5 polymorphisms in HIV/AIDS context." (PMID 34262570, 2021). "Increased NK cell activity reflected by higher cytotoxic capacity, IFN-γ and chemokines (CCL3, CCL4, and CCL5) production, has been associated with resistance to HIV infection and delayed AIDS progression, demonstrating the importance of these cells in the antiviral response." (PMID 30386329, 2018). "The higher functionality, in terms of CCL4 secretion, of educated KIR3DL1+ NK cells may be a mechanism underlying the superior viral control and slower time to AIDS observed in epidemiological studies for some carriers of KIR3DL1hmz/Bw4 compared to carriers of other KIR/HLA genotypes." (PMID 28893287, 2017). "However, CCL4 may play a role in HIV Type 1 transmission, AIDS disease progression, and acute kidney injury." (PMID 25340798, 2014). "A clinical trial for HIV/AIDS vaccine designed to evaluate non-neutralizing functions of vaccine-induced antibodies confirmed the correlation between HIV-specific antibodies and secretion of IFN-γ, CCL4 and expression of the degranulation marker CD107a on NK cells, from vaccine recipients." (PMID 30386329, 2018).
cerebral malaria (5 papers, 2013 to 2024). A sequestration of Plasmodium falciparum in the brain, which can cause coma and/or seizures. "Other studies have shown that circulating levels of CXCL8 and CCL4 correlated with parasite density, and when found in the cerebrospinal fluid they can predict cerebral malaria mortality." (PMID 39830896, 2024). "However, future analysis is necessary to confirm or investigate this hypothesis, mainly by evaluating the production levels of CCL2, CCL4, CXCL4, CXCL8, CXCL10, and the receptors CXCR3 and CCR2, correlated with susceptibility to cerebral malaria and lung inflammation." (PMID 38256880, 2023).
chronic lymphocytic leukemia (5 papers, 2019 to 2025). "The expression of CCL3 and CCL4 is increased in chronic lymphocytic leukemia, and can be used as biomarkers in the therapy targeting chronic lymphocytic leukemia." (PMID 36639681, 2023). "High CCL4 protein level was also found in chronic lymphocytic leukemia B cells co‐cultures with nurse‐like cells, and the induction of CCL4 was abolished by a Syk inhibitor (R406), suggesting that nurse‐like cells induce the chemokine via B‐cell receptor (BCR) activation." (PMID 41208700, 2025).
cognitive defects (5 papers, 2021 to 2024). "Additionally, PARK6-associated PD patients have also shown PINK1 deficiency and its impact on increased generation of pro-inflammatory cytokines and chemokines (e.g., IFNβ1, IL-6, IL-12, IL-13, CCL2, CCL4, and CXCL1), loss of NCs, and the development of cognitive defects." (PMID 34239490, 2021). "In this paper, we review the roles and regulatory mechanisms of pro-inflammatory chemokines (CCL2, CCL3, CCL4, CCL5, CCL11, CCL20, and CXCL8) in cognitive impairment." (PMID 39011039, 2024).
esophageal cancer (5 papers, 2019 to 2022). A primary or metastatic malignant neoplasm involving the esophagus. "Moreover, a study in esophageal cancer reported that CCL4 recruits cytotoxic tumor infiltrating lymphocytes." (PMID 36131935, 2022). "The chemokines CCL4 and CCL20 have been shown to recruit subsets of T cells in esophageal carcinoma, where CCL4 expression was correlated with the expression of CD8 and GZMB." (PMID 30451357, 2019).
experimental autoimmune encephalomyelitis (5 papers, 2015 to 2023). An autoimmune demyelinating disease of the central nervous system that is produced experimentally in animals by the injection of homogenized brain or spinal cord in Freund's adjuvant. "Tregs deficient for expression of CCL4 were impaired in their ability to suppress experimental autoimmune encephalomyelitis or islet allograft rejection in murine models." (PMID 30169503, 2018). "Moreover, the upregulation of Ccl2, Ccl3, Ccl4, Ccl7, Cxcl9, and Cxcl10 is also related to the acute phase of experimental autoimmune encephalomyelitis." (PMID 35911717, 2022). "Furthermore, combined neutralization of all three known CCR5 ligands (CCL3, CCL4, CCL5) has been shown to ameliorate the course, i.e., reduce disease activity, in MS animal models of experimental autoimmune encephalomyelitis." (PMID 33324890, 2019). "CXCL10/IP-10, CCL2/MCP-1, CCL3/MIP-1a, CCL4/MIP-1b, CCL5/Rantes, CCL7/MCP-3 and CXCL9/Mig are among the described proinflammatory chemokines produced by immune cells and CNS glia in MS and in the animal model of MS, experimental autoimmune encephalomyelitis (EAE)." (PMID 26039252, 2015).
liver failure (5 papers, 2015 to 2024). A liver disease characterized by the liver losing or has lost all of its function. "The results showed that tadalafil and/or L. sativum, especially in combination, performed well to cure acute mild liver failure caused by CCL4." (PMID 38413963, 2024). "The only advent of kidney failure, liver failure, and need for pressors was associated with elevation of specific markers (CCL4, CD40, CXCL5, and IL-15), but our findings’ interpretation needs more broad context." (PMID 34177897, 2021). "The CCL4-induced liver failure group had considerably greater (p < 0.0001) serum albumin levels than the control saline-treated group, whereas total protein serum levels were significantly lower." (PMID 38413963, 2024). "Rats with CCL4-induced liver failure had higher levels of blood liver enzymes (AST, ALT, and ALP) than those with saline." (PMID 38413963, 2024). "The combination of tadalafil and L. sativum significantly increased time spent in open arms and closed arms compared to the CCL4-induced liver failure group." (PMID 38413963, 2024). "There was a significant (p < 0.0001) decline in serum albumin levels after treatment with tadalafil and L. sativum alone or in combination with CCL4-induced liver failure, with a greater drop in the L. sativum-treated group and combination-treated group." (PMID 38413963, 2024). "However, time spent in closed arms increased significantly in CCL4-induced liver failure, tadalafil-treated, and L. sativum-treated groups, but there was no significant change when both tadalafil and L. sativum combinations were used compared to control rats." (PMID 38413963, 2024). "Furthermore, in CCL4-induced liver failure, total protein serum levels increased significantly (p < 0.001) only following treatment with the tadalafil- L. sativum combination." (PMID 38413963, 2024). "Treatment with L. sativum and tadalafil, either alone or in combination, resulted in a significant (p < 0.0001) decrease in IL-1β and TNF-α levels in the liver tissue when compared to the CCL4-induced liver failure group, with a possibly superior effect for the tadalafil-L." (PMID 38413963, 2024). "Most researchers used paracetamol (APAP), LPS, D-GalN, CCL4, TNF-α, TGF-β1, and multiplicity of infection(MOI) to induce the liver failure model." (PMID 38172209, 2024). "Liver failure was induced by hepatotoxic drugs, such as APAP, LPS, D-GalN, CCL4, human serum albumin (HSA), concanavalin-A, and TNF, or surgical simulation including cecal ligation puncture, partial hepatectomy, and bile duct ligation." (PMID 38172209, 2024). "A study in India reported a significantly increased frequency of circulating NKT cells (CD3+CD56+CD16+) and higher levels of MIP-1β/CCL4 among patients with acute HBV infection, but not HBV-induced liver failure, compared to healthy controls." (PMID 26074921, 2015).
lymphoma (5 papers, 2017 to 2024). A malignant (clonal) proliferation of B- lymphocytes or T- lymphocytes which involves the lymph nodes, bone marrow and/or extranodal sites. "Microarray profiling and cytokine array screening revealed that EBNA2 is associated with upregulation of the chemokines CCL3 and CCL4 in lymphoma cells." (PMID 28036258, 2017). "Therefore, maintained cytokine production in the presence of ibrutinib owing to the C481S mutation suggests that CCL3 and CCL4 may shape a supportive lymphoma microenvironment and thus contribute to in vivo selection of malignant B cells that express mutant BTK." (PMID 32899476, 2020). "Based on these findings, we propose that a pathway involving EBNA2/Btk/NF-κB/CCL3/CCL4 plays a key role in doxorubicin resistance, and therefore, inhibition of specific components of this pathway may sensitize lymphoma cells to doxorubicin." (PMID 28036258, 2017). "In accordance with ibrutinib-sensitive cytokine production by activated lymphoma cells, the elevated blood levels of CCL3 and CCL4 in CLL patients show strong reduction upon ibrutinib treatment compared to other cytokines." (PMID 32899476, 2020). "Since EBV+ lymphomas secrete high quantities of CCL3, CCL4, CCL22, and CXCL10 compared to EBV- lymphoma lines, the high expression of CCR5, CCR4, and CXCR3 on both EBV VST groups may indicate complementary/alternate axes of migratory mechanisms." (PMID 39011042, 2024). "In addition, LOAd703-infected lymphoma cells upregulated the secretion of several chemokines (CXCL10, CCL17, CCL22, CCL3, CCL4) essential for immune cell homing, leading to enhanced CAR T-cell migration." (PMID 33666760, 2021).